RNU6-1306P (RNA, U6 small nuclear 1306, pseudogene)
Gene: Small nuclear RNA gene on chromosome 11 (63,882,587 to 63,882,685, reverse strand). Ensembl gene ENSG00000202089.
Homologues: Orthologues: chimpanzee U6 (100% identical), macaque U6 (90% identical), pig U6 (70% identical). Paralogues in human: RNU6-592P (88% identical), RNU6-536P (86% identical), RNU6-1011P (85% identical), RNU6-1122P (85% identical), RNU6-132P (85% identical), RNU6-16P (85% identical), RNU6-869P (85% identical), RNU6-1005P (84% identical), RNU6-1060P (84% identical), RNU6-12P (84% identical), RNU6-13P (84% identical), RNU6-15P (84% identical), and 1283 more.